SIRT6 (sirtuin 6)
Diseases named in the same sentence as SIRT6 in open-access papers (continued):
Sharing a sentence is not in itself a finding about the gene and the disease.
Sepsis (16 papers, 2012 to 2026). Sepsis is defined as life-threatening organ dysfunction caused by a dysregulated host response to infection. "Notably, SIRT6 overexpression alleviates AKI caused by sepsis." (PMID 34412625, 2021). "Others also found that Sirt6 activation by UBCS039 can shift macrophages from M1 type to M2 type in sepsis-induced acute respiratory distress syndrome, hepatic injury and peripheral nerve injury." (PMID 41530841, 2026). "Studies have shown that SIRT6 eases sepsis‐elicited acute respiratory distress syndrome via promoting macrophage M2 polarization." (PMID 36988243, 2023). "Several studies have recently demonstrated the renal protective effect of SIRT6-induced autophagy in sepsis-induced AKI, hypertensive cardiorenal injury, podocyte injury, and cadmium-induced renal damage, respectively." (PMID 36160707, 2022). "Altogether, these findings illustrate that USP10 alleviates sepsis-induced AKI by regulating Sirt6-mediated Nrf2/ARE signaling pathway, proposing a novel target for the clinical treatment of AKI." (PMID 34412625, 2021). "Evidence suggests that the SIRT6 oxidation during the hyper-inflammation of sepsis modulates its glycolytic function." (PMID 35052507, 2021). "Remarkably, repression of HIF-1α by SIRT6 drives a metabolic shift from glycolysis to fatty acid oxidation during sepsis." (PMID 34828304, 2021). "Although known in cancer and ageing literature, the role of SIRT6 in modulating sepsis-induced oxidative stress via SOD or activation of NRF-2 target gene expression needs further evaluation." (PMID 35052507, 2021). "In the present study, we found that Sirt6-mediated Nrf2/ARE signaling alleviates sepsis-induced AKI via USP10." (PMID 34412625, 2021). "SIRT1 and SIRT6 have a major role on the regulation of the acute inflammatory response during sepsis by controlling the transition from an early inflammatory response to a late stage where immune cells enter in a resting state and resolve the infection." (PMID 34828304, 2021). "This study highlights the relevance of SIRT6 as an important player in inflammatory reactions of the human endothelium in the context of sepsis." (PMID 23132960, 2012). "A previous study has shown that SIRT6 expression is decreased in sepsis‐induced lung injury." (PMID 36988243, 2023). "In addition, direct and reversible cysteine thiol 144 oxidation in SIRT6 during sepsis hyperinflammation regulates its glycolytic function, contributing to immunometabolic paralysis in human and mouse sepsis monocytes." (PMID 35883885, 2022). "Moreover, USP10 attenuates sepsis-induced oxidative stress in renal tissues by increasing SIRT6 stability and activating the NRF2 /ARE signaling pathway." (PMID 34412625, 2021). "In addition, the role of USP10 in sepsis-induced oxidative stress in renal tissues via SIRT6-mediated NRF2 /ARE signaling pathway was investigated." (PMID 34412625, 2021). "We speculated that this motif in SIRT6 would be important for control of its function during acute inflammation in the reprogramming of immunity to an immunosuppressive state during prolonged sepsis." (PMID 28887543, 2017). "Increased glycolysis during the early inflammatory phase of sepsis results in high concentration of NAD+, which induces SIRT6 and SIRT1 activity." (PMID 34828304, 2021). "It has been reported that SIRT6 and SIRT3 work closely with SIRT1 in the sepsis adaptation stage to jointly regulate energy shifts, promote mitochondrial-nuclear exchange, and accelerate the development of immunosuppression." (PMID 30533222, 2018). "Sulfenylation of SIRT6 occurs in THP1 cells and primary human promonocytes during inflammation and in splenocytes from mice with sepsis." (PMID 28887543, 2017). "A block in glycolysis associated with monocyte deactivation by endotoxin, a process contributing to immunometabolic paralysis in human and mouse sepsis monocytes, can be reversed by increasing H2O2 and sulfenylating SIRT6." (PMID 28887543, 2017).
Sepsis (continued). "We discovered that in cell and lean mouse models of sepsis that nuclear SIRT-1 couples with nuclear NFκB p65/ RelB, nuclear SIRT-6 and mitochondrial SIRT-3 as homeostasis checkpoints during acute sepsis-inflammation." (PMID 27500833, 2016). "Moreover, in sepsis‐evoked ALI, SIRT6 positively regulates Nrf2 expression, activates Nrf2‐mediated anti‐inflammatory and antioxidant enzymes, and can effectively alleviate LPS‐induced inflammation of HUVECs." (PMID 36988243, 2023). "However, studies of SIRT5, SIRT6, and SIRT7 relating to the pathogenesis of sepsis are rare and need to be explored in the future." (PMID 30533222, 2018). "Other key signaling pathways include sirtuin 6 (SIRT6), which promotes anti-inflammatory macrophage polarization and autophagy in septic lungs, and ankyrin demonstrated domain 22 (ANKRD22), which enhances M1 polarization via interferon regulatory factor 3 (IRF3) in sepsis-induced ARDS." (PMID 41488672, 2025). "Indeed, in a model of sepsis, NAD+ levels have been shown to regulate a metabolic shift in macrophages from glycolytic metabolism to increased FAO by a mechanism involving SIRT1 and SIRT6." (PMID 34828304, 2021). "Besides, the oxidation of cysteine on SIRT6 and SIRT2 as well as the nitrosylation of SIRT1 could decrease their expression, respectively, during sepsis." (PMID 30533222, 2018). "We utilized two different models validate this observation of SIRT6 sulfenylation: normal monocytes isolated from peripheral human blood and stimulated with LPS, and mouse splenocytes isolated from mice subjected to cecal ligation and puncture (CLP) to induce acute systemic infection from sepsis." (PMID 28887543, 2017).
type 2 diabetes (16 papers, 2017 to 2026). "SIRT6 is downregulated in the vascular walls of patients with type 2 diabetes mellitus (T2DM) and GDM." (PMID 41471349, 2025). "Enhanced SIRT6 levels defend against diet-induced type 2 diabetes by improving insulin sensitivity in muscle and liver, while inhibiting SIRT6 improves glucose tolerance 33,34." (PMID 38904020, 2024). "An inverse correlation of Sirt6 expression in visceral fat with BMI and WC was also observed in subjects with type 2 diabetes." (PMID 31113929, 2019). "The reduced Sirt6 expression was also observed in the kidney from db/db mice, another in vivo model of type II diabetes." (PMID 28871079, 2017). "Further research is needed to explore optimal methods for modulating SIRT6 in type 2 diabetes." (PMID 38904020, 2024). "Several proteins involved in glucose metabolism have been linked to type 2 diabetes, including, Glutamine fructose-6-phosphate amidotransferase (GFPT or GFAT), Mono-ADP-ribosyltransferase sirtuin-6 (SIRT6), 11-β hydroxysteroid dehydrogenase type 1 (11β-HSD1) and protein phosphatase (PPM1B)." (PMID 37894680, 2023). "In addition, a SIRT6 inhibitor with quinazolinedione structure (named 1) was administered to mice in an in vivo study of SIRT6 inhibition for treating type 2 diabetes." (PMID 32736564, 2020). "In addition, given the fact that SIRT6 regulates insulin signaling and the expression of the glucose transporters GLUT1 and GLUT4, we previously tested 1 in a mouse model of type 2 diabetes." (PMID 32736564, 2020).
liver fibrosis (15 papers, 2017 to 2026). "Sirt6 overexpression prevents hepatic fibrosis by curbing inflammation and oxidative stress, and Sirt6 deficiency results in progressive renal inflammation and fibrosis." (PMID 30881591, 2019). "The specific knockout of SIRT6 in T cells or macrophages causes the attack of immune cells and the excessive secretion of inflammatory factors, which ultimately promotes the occurrence of liver fibrosis." (PMID 37298491, 2023). "Studies in mice fed a high-fat, high-fructose diet for 16 weeks and in liver samples from patients with non-alcoholic steatohepatitis (NASH) have shown that SIRT6 plays a regulatory role in the progression of NASH to liver fibrosis." (PMID 38294557, 2024). "The anti-fibrotic function of Sirt6 was achieved by regulating the TGFβ-Smad2/3 pathway in stellate cells activation as well as liver fibrosis." (PMID 38789630, 2024). "Based on correlation between Sirt6 and fibrosis/Smad signaling pathway, it had been reported that Sirt6 directly interacted with Smad2 in hepatic fibrosis and there was a physical interaction between Sirt6 and Smad3 in hepatic stellate cells." (PMID 38789630, 2024). "Hepatocyte-specific knockout of SIRT6 in mice aggravated liver fibrosis, and reduced SIRT6 expression levels were observed in the livers of NASH patients as the disease progressed to fibrosis." (PMID 38294557, 2024). "In diet- or chemical-induced liver fibrosis mouse models, hepatic Sirt6 protein levels are also significantly decreased compared to those in normal animals." (PMID 36831330, 2023). "Regarding the anti-liver fibrosis effects of Sirt6 on activated HSCs, GS predominantly prevented accumulations of collagen type 1 deposition during TGF-β1-mediated fibrotic stimulus on LX-2 cells." (PMID 36670959, 2022). "In addition, emerging data suggest that SIRT6 modulates hepatic stellate cell activation and fibrogenic signaling pathways, thereby linking epigenetic regulation to the development of liver fibrosis." (PMID 42193040, 2026). "HSC-specific Sirt6 knockout mice are more susceptible to diet- (high-fat and high-cholesterol) or chemical (CCl4 or DDC: 5-diethoxycarbonyl-1,4-dihydrocollidine)-induced liver fibrosis than WT mice." (PMID 36831330, 2023). "Indeed, SIRT6 is demonstrated to protect against liver fibrosis by inactivating hepatic stellate cells." (PMID 36172184, 2022). "Although Sirt6 has been recognized as a key modulator in cardiac and liver fibrosis, to the best of our knowledge, whether Sirt6 is involved in pulmonary EMT process has yet to be identified." (PMID 28977842, 2017). "Sirt6 (gene ID: 51548), also known as sirtuin 6 or SIR2L6, is a member of the sirtuin family of class III NAD+-dependent deacetylases, which affect the physiology of multiple cell types, tissues, and phenotypes associated with aging, cancer, metabolic disorders, and liver fibrosis." (PMID 34122724, 2021). "Zhong and colleagues' results indicated that Sirt6 alleviates EMT and liver fibrosis in hepatic stellate cells by deacetylating conserved lysine residues (K333 and K378) on Smad3." (PMID 34122724, 2021). "However, another study showed that SIRT6 alleviated liver fibrosis by deacetylating and inactivating SMAD2 in hepatic stellate cells of an experimental liver fibrosis model." (PMID 37777567, 2023). "Sirtuin 6 contributes to YAP/TAZ deacetylation and reprograming the TEA domain transcription factor complex composition, thereby reducing the expression of downstream liver fibrosis targeting genes and ultimately delaying the development of liver fibrosis." (PMID 37576865, 2023). "It has been demonstrated that SIRT6 inhibits Smad3 activation, a member of the Smad family involved in TGF-β signaling, through H3K9 deacetylation, thereby suppressing the expression of key genes related to liver fibrosis and contributing to fibrosis regression." (PMID 38294557, 2024).
liver fibrosis (continued). "Mechanistic studies have revealed that SIRT6 inhibits TGF-β-induced activation of hepatic stellate cells by deacetylating specific sites (K333 and K378) on Smad3, resulting in the downregulation of liver fibrosis-related genes and the inhibition of fibrosis progression." (PMID 38294557, 2024).
osteosarcoma (15 papers, 2018 to 2026). A usually aggressive malignant bone-forming mesenchymal neoplasm, predominantly affecting adolescents and young adults. "Higher expression of CSNK2A1 and phosphorylated SIRT6 was associated with shorter survival in osteosarcoma patients." (PMID 34359939, 2021). "SIRT6-positivity had a 6.797 fold greater risk of death of osteosarcoma patients (95% CI, 2.129–21.702) and had a 6.516 fold greater risk of relapse of tumor or death of patients (95% CI, 2.234–19.001)." (PMID 33198792, 2020). "Immunohistochemical expression of SIRT6 was significantly associated with shorter overall survival and relapse-free survival of osteosarcoma patients, especially in patients who received adjuvant chemotherapy." (PMID 33198792, 2020). "A factor significantly associated with SIRT6 expression was latent distance metastasis of osteosarcoma." (PMID 33198792, 2020). "Especially, SIRT6-positivity indicated a 4.012 fold greater risk of death of osteosarcoma patients (95% CI, 1.419–11.344; P = 0.009) and had a 4.151 fold greater risk of relapse of tumor or death of patients (95% CI, 1.570-10.971; P = 0.004)." (PMID 33198792, 2020). "SIRT6 expression predicted a 6.988 fold greater risk of death of osteosarcoma patients (95% CI, 1.439–33.930; P = 0.016) and had a 6.930 fold greater risk of relapse of tumor or death of patients (95% CI, 1.727–27.814; P = 0.006)." (PMID 33198792, 2020). "With this cut-off point, SIRT6 positivity was significantly associated with latent distant metastasis of osteosarcoma patients (P = 0.005)." (PMID 33198792, 2020). "SIRT6 has been implicated as a critical regulator of chemoresistance in osteosarcoma." (PMID 41463311, 2025). "Furthermore, high expression of SIRT6 was significantly associated with more metastasis and shorter OS and disease-free survival of osteosarcoma patients." (PMID 33198792, 2020). "In osteosarcoma cells, SIRT6-mediated invasiveness was associated with MMP9 signaling." (PMID 30524965, 2018). "In comparison, patients with osteosarcoma who express a high level of SIRT6 exhibit malignant clinical features and have a worse survival rate, with in vitro experiments indicating that SIRT6 overexpression aided MG63 cell motility and invasion." (PMID 35172823, 2022). "Recently, therapeutic applications targeting the DNA damage repair pathway by using a PARP inhibitor and by inhibiting SIRT6 have been reported in osteosarcoma." (PMID 34359939, 2021). "An interesting finding of this study is that the CSNK2A1-mediated phosphorylation of SIRT6 is important in the treatment efficacy of doxorubicin in osteosarcoma cells." (PMID 34359939, 2021). "It has been demonstrated that curcumin can inhibit SIRT6 expression through upregulating the expression of miR-33b-5p expression resulting in the inhibition of osteosarcoma cell migration and invasion." (PMID 34671398, 2021). "In osteosarcoma cells, the inhibition of SIRT6 sensitized cells to the cytotoxic effect of doxorubicin." (PMID 34359939, 2021). "In this sub-group of osteosarcoma patients, SIRT6 expression was an independent indicator of poor prognosis of osteosarcoma patients with univariable and multivariable analyses." (PMID 33198792, 2020). "In U2OS and KHOS/NP osteosarcoma cells, knock-down of SIRT6 significantly potentiated apoptotic effects of doxorubicin and SIRT6 overexpression induced resistance to doxorubicin." (PMID 33198792, 2020). "LncRNA HIF1A antisense RNA 2 (HIF1A-AS2) was identified as ceRNA by sponging miR-33b-5p to facilitate cell survival and migration and modulate the expression of sirtuin 6 (SIRT6) in osteosarcoma." (PMID 33117693, 2020). "We evaluated the prognostic significance of SIRT6 in 37 osteosarcomas and investigated the therapeutic efficacy of SIRT6 on the anticancer effects of doxorubicin, olaparib, and ATM inhibitor." (PMID 33198792, 2020).
osteosarcoma (continued). "Based on the prognostic significance of SIRT6 expression in osteosarcoma patients, especially in the patients who received adjuvant chemotherapy, we evaluated the effects of SIRT6 expression on the anti-tumor activity of doxorubicin in osteosarcoma cells." (PMID 33198792, 2020). "Based on the cytotoxic activity of doxorubicin, we further evaluated the effects of SIRT6 expression on apoptosis of osteosarcoma cells when co-treated with 0.1 μM doxorubicin." (PMID 33198792, 2020). "In this study, we demonstrate that high expression of SIRT6 is significantly associated with shorter survival of osteosarcoma patients as an independent indicator of shorter OS and RFS of osteosarcoma patients." (PMID 33198792, 2020). "For example, SIRT6 plays an oncogenic role in osteosarcoma and papillary thyroid cancer." (PMID 39845013, 2025). "Notably, pharmacological blockade of SIRT6 or inhibition of CK2α (e.g., with emodin) synergistically enhances the anti-tumor activity of doxorubicin in osteosarcoma models." (PMID 41463311, 2025). "As we previously reported, CSNK2A1 phosphorylates SIRT6 on Ser338 among the four phosphorylation sites of SIRT6, and expression of CSNK2A1 was associated with phosphorylation of SIRT6 on Ser338 on U2OS and KHOS/NP osteosarcoma cells." (PMID 34359939, 2021). "However, there is a limitation to the use of inhibitors of PARP and SIRT6 in sarcomas, including osteosarcoma." (PMID 34359939, 2021). "Therefore, we conducted a more precise evaluation of the role of CSNK2A1-SIRT6 in human cancer, especially in osteosarcoma, and we showed that the phosphorylation status of SIRT6 on Ser338 is important in CSNK2A1-mediated chemoresistance in osteosarcoma cells." (PMID 34359939, 2021). "Furthermore, treatment with KU-55,933 or olaparib synergizes with the anti-cancer effect of doxorubicin in both control osteosarcoma cells and osteosarcoma cells with induced overexpression of SIRT6." (PMID 33198792, 2020). "In conclusion, our results indicate that SIRT6 expression might be useful as a novel prognostic indicator for osteosarcoma patients, especially for patients who received adjuvant chemotherapy." (PMID 33198792, 2020). "Furthermore, the role of SIRT6 in the progression of osteosarcoma has been reported controversially." (PMID 33198792, 2020). "In addition, overexpression of SIRT6 induced resistance to doxorubicin-mediated apoptosis of osteosarcoma cells and knock-down of SIRT6 sensitized doxorubicin-mediated apoptosis of osteosarcoma cells." (PMID 33198792, 2020). "In addition, SIRT6-positivity was significantly associated with shorter OS and RFS in subgroups of osteosarcoma patients who received adjuvant chemotherapy." (PMID 33198792, 2020). "Therefore, we evaluated the effect of co-treatment of doxorubicin and an ATM inhibitor/PARP inhibitor in osteosarcoma cells in which the overexpression of SIRT6 had been induced." (PMID 33198792, 2020). "This study suggests that suppression of SIRT6 in combination with doxorubicin might be an effective modality in the treatment of osteosarcoma patients, especially for osteosarcomas with shorter survival with high expression of SIRT6." (PMID 33198792, 2020). "In addition, we performed flow cytometry analysis for apoptosis after co-treatment of doxorubicin and an ATM inhibitor/PARP inhibitor in osteosarcoma cells in which the overexpression of SIRT6 had been induced." (PMID 33198792, 2020). "Moreover, the effects of SIRT6 on the proliferation and apoptosis of osteosarcoma cells under the treatment of doxorubicin raise the possibility that the SIRT6-mediated DNA damage repair pathway might affect the cytotoxic effect of doxorubicin." (PMID 33198792, 2020).